POSTN (periostin)
Diseases named in the same sentence as POSTN in open-access papers (continued):
Sharing a sentence is not in itself a finding about the gene and the disease.
cancer (continued). "The expression level of POSTN in healthy adult tissues is very low, whereas it is found highly upregulated in a wide spectrum of inflammatory diseases and cancers." (PMID 36102377, 2022). "TGF-β1 induces cancer metastasis and fibroblast activation, which is related to the expression of POSTN." (PMID 35281822, 2022). "POSTN has also been confirmed to regulate the development of several types of human cancers by binding to the integrins to activate the Akt/PKB and FAK-mediated signaling pathways." (PMID 35163164, 2022). "Given the well-known periostin functions in cancer, the question remains as to which mechanism is at work." (PMID 36224629, 2022). "It has been shown that due to its tyrosine- and histidine-rich regions, POSTN binds to integrin receptors (αvβ3, αvβ5, α6β4) that are present on the surface of cancer cells, thus influencing the regulation of intracellular signaling pathways (PI3K, AKT/PKB)." (PMID 36077762, 2022). "Periostin is known to be present in many different cancer cell types as it promotes cellular survival, angiogenesis, and resistance to hypoxia-induced cell death." (PMID 36536419, 2022). "The role of periostin in multiple solid tumors is pleiotropic; therefore, it seems that exploring its regulation is crucial in cancer research." (PMID 35056404, 2022). "Periostin is rarely detected in most normal adult tissues, but is highly induced in lesions, inflammation, and several forms of cancers, including pancreatic, ovarian, lung, breast, gastric, esophageal and colon." (PMID 35056404, 2022). "POSTN is also thought to play an important role in lymphangiogenesis, which is crucial for the formation of metastases, which translates into cancer progression." (PMID 36077762, 2022). "POSTN regulates the proliferation, angiogenesis, invasion, and metastasis of cancer cells by interacting with integrins." (PMID 35832544, 2022). "In humans, high expression of POSTN has been detected in various types of cancer, including breast, ovarian, lung, prostate, kidney, intestine, and pancreas." (PMID 35865633, 2022). "POSTN is a matricellular protein that has been found to affect multiple processes in cancer development." (PMID 35884543, 2022). "Statistically, differences in POSTN expression in cancer cells were also noted regarding lymph node status." (PMID 35163164, 2022). "To evaluate the role of POSTN in cancer prognosis, we examined the correlation between POSTN expression and overall survival, progression-free survival, and post-progression survival using the Kaplan-Meier plotter database." (PMID 35508298, 2022). "Periostin is an extracellular matrix protein and is known to be involved in the epithelial–mesenchymal transition, a key mechanism in the initial stages of cancer pathogenesis." (PMID 35406434, 2022). "The dysregulation of periostin expression in several cancers indicates that it plays an important role in cancer development and progression." (PMID 36224629, 2022). "Addressing these questions will be crucial to understanding how periostin functions and to developing new treatment strategies for cancer." (PMID 36224629, 2022). "Some studies have shown that blocking of periostin function by anti-periostin antibodies are an effective cancer treatment strategy." (PMID 36224629, 2022). "In general, it should be noted that the effect of periostin on the proliferation of cancer cells varies depending on the cell types." (PMID 36224629, 2022). "In the MMTV-PyMT mouse breast cancer model, infiltrating cancer cells need to induce stromal POSTN expression to initiate lung metastatic colonisation." (PMID 35260891, 2022). "Periostin is an extracellular matrix protein that affects cancer cell proliferation, migration, and epithelial to mesenchymal transition." (PMID 35669467, 2022). "The production of POSTN then augments Wnt signalling to facilitate cancer stem cell maintenance and promote metastasis." (PMID 35260891, 2022).
cancer (continued). "The 5-year overall survival and cancer-specific survival rates were 47% and 51%, respectively, in patients with high stromal periostin expression, and 86% and 90%, respectively, in patients with low stromal periostin expression." (PMID 35850759, 2022). "Several studies have introduced effective methods for blocking periostin signaling pathways in preclinical models of cancer." (PMID 36224629, 2022). "In pancreatis cancer, a high expression of periostin induces tubule formation, whereas periostin knockdown results in decreasing VEGF expression." (PMID 35056404, 2022). "Periostin can affect cancer cells to survive under hypoxic conditions by inhibiting stress-induced apoptosis." (PMID 36224629, 2022). "In our study, we found significantly higher concentrations of periostin levels in cancer tissues than in tissue margins (p < 0.0001)." (PMID 35056404, 2022). "In many cancers, periostin is mostly found in the cancer stroma, but it is also detected in epithelial cancer cells and in both epithelial and stromal cancer cells." (PMID 36224629, 2022). "Inhibiting periostin using antibody binding αvβ3 integrin region has been developed and proved effective in cancer cells, however in vivo successful is still pending." (PMID 35707463, 2022). "We investigated the mRNA expression of POSTN among multiple human cancer types using the Oncomine database and Timer database." (PMID 35508298, 2022). "Depletion of periostin from the serum inhibited proliferation of cancer cells while addition of periostin promoted cancer cell proliferation in vitro." (PMID 35669467, 2022). "POSTN is an established diagnostic biomarker for patients with IPF that is matrix specific and is located in cancer-associated fibroblasts." (PMID 35480306, 2022). "Subsequent Cox multivariate analysis showed that LVI (p = 0.032, hazard ratio = 2.61) and high stromal periostin expression (p = 0.020, hazard ratio = 3.07) were independent predictors of cancer-specific survival." (PMID 35850759, 2022). "On the other hand, increased levels of CTGF, FN and periostin in the circulation are consistent with the increased cancer progression with higher proliferation and metastasis characteristics." (PMID 35406672, 2022). "Up-regulation of KDR by periostin (POSTN) induces angiogenesis which was an important step in the development of cancer." (PMID 35057823, 2022). "Using patient-derived omentum cancer-associated fibroblasts from high-grade serous ovarian cancers (Om-CAFs), we show that DDR2-depletion leads to decreased expression of POSTN." (PMID 35884543, 2022). "Patients with high percentage of cancer associated fibroblasts and expression of TIMP3 but low expression of COL1A1, COL3A1, MMP1 and POSTN were associated with sensitivity to paclitaxel." (PMID 35480306, 2022). "In cancer cells, periostin acts as a ligand for alpha-V/beta-3 and alpha-V/beta-5 integrins to support the adhesion and migration of epithelial cells." (PMID 36536419, 2022). "Previous in-depth studies of POSTN showed that it functions in cell recruitment, adhesion, and other normal physiological processes, but also has high expression in many malignant tumors." (PMID 35057799, 2022). "The data suggest that POSTN plays a crucial role in the multistep cascade process of cancer metastasis." (PMID 35163164, 2022). "It is up-regulated in metastasis and can influence the size and number of metastatic lesions, indicating that periostin plays a critical role in the formation and remodeling of cancer tissue microenvironments." (PMID 36224629, 2022). "POSTN over-expression has been observed in several cancer types including breast, lung, colorectal, ovary and prostate cancers." (PMID 35567669, 2022). "Unraveling the complex network of connections between extracellular matrix proteins, such as periostin, and the inflammatory infiltrate in response to cancer, is crucial for the development of further therapeutic options." (PMID 35056404, 2022).
cancer (continued). "Now, there is a degree of incompatibility between periostin expression and clinico-pathological parameters in some types of cancer." (PMID 36224629, 2022). "POSTN is a cell adhesion protein overexpressed by CAFs in a number of cancers including CRC and has been suggested as a poor prognostic factor in a handful of studies." (PMID 34874125, 2022). "Data from studies on gastric cancer cell lines provide evidence that periostin is a hypoxia response gene and mediates communication between cancer cells and hypoxic endothelial cells, in part, through VEGF signaling." (PMID 35056404, 2022). "Some investigators have claimed that the mRNA expression of POSTN occurs only in stromal cells, or in cancer cells." (PMID 33905434, 2021). "Studies on periostin expression in human cancers have demonstrated an increased expression in a variety of solid tumours where it is associated with their malignant behaviour (Extensively reviewed by:)." (PMID 34205668, 2021). "In many cancer models, the expression of POSTN and its receptors also plays a crucial role in tumorigenesis." (PMID 34513869, 2021). "We also considered that periostin secreted by activated fibroblasts is most likely to be contained in exosomes and reach cancer cells hematogenously, but further experiments should be performed to elucidate the exact mechanisms of the interaction." (PMID 34702952, 2021). "It is also possible, that while cell senescence and other disease processes promoting cancer are dominant in older age, periostin secretion as a result of cardiac adaptive remodeling secondary to AS is more dominant in younger age." (PMID 34696798, 2021). "Periostin is a secreted protein frequently overexpressed in many cancer types, with its expression being correlated with metastasis and poor patient survival." (PMID 34200480, 2021). "TGF-β3 rooted from cancer cells fortifies a favorable niche to colonize a foreign site by stimulating fibroblast-derived POSTN, which is crucial for initiating breast cancer cell colonization at the lung by maintaining CSC properties via the Wnt signaling." (PMID 34760886, 2021). "In particular, periostin, or osteoblast-specific factor 2, regulates collagen fibrillation, activates Wnt signaling, supports cancer stem cells and metastasis." (PMID 34439102, 2021). "Using these data, we assessed POSTN levels across cell types and found that its expression is largely specific to fibroblasts and cancer cell populations." (PMID 34809697, 2021). "Why can we detect POSTN exon 17 on both the surface and interior of cancer cells even though the POSTN short fragment accumulates mainly on the surfaces of cancer cells?" (PMID 33919736, 2021). "Cancer stem cells (CSCs) have been shown to express POSTN via either autocrine or paracrine pathways; this process plays an important role in the functional maintenance of CSCs." (PMID 34513869, 2021). "Immunohistochemically, periostin was highly expressed in cancer stroma derived from mice injected with NSCLC cells combined with DIPF." (PMID 34702952, 2021). "While regulating the EMT, POSTN plays a role in cancer stemness via interacting with protein tyrosine kinase 7 (PTK7) and propagates the cancer stem cell (CSC)-like phenotype via PTK7-Wnt/β-Catenin signalling." (PMID 33739025, 2021). "Tenascin C (TNC), a secreted glycoprotein that binds to a variety of ECM proteins, such as periostin, fibronectin, integrins, and collagens, is overexpressed in several pathological conditions, including inflammation, wound healing, and cancer." (PMID 34200480, 2021). "However, we report in this study that the effects of POSTN on cancer can be detected by antibodies against the POSTN C-terminal, which suggests that different POSTN variants may exist in different regions in the cancer microenvironment." (PMID 33919736, 2021). "Periostin has been shown to regulate key aspects of cancer cell behaviors, including cell proliferation, migration, and ECM remodeling." (PMID 33946915, 2021).
cancer (continued). "In this model, cardiac remodeling was associated with increased tumor growth and metastasis seeding, which was suggested to be mediated by periostin, a matrix protein that enhances cancer cell proliferation." (PMID 34696798, 2021). "CAF-derived POSTN plays a role in cancer stemness via interacting with Protein tyrosine kinase 7 (PTK7) in HNSCC26." (PMID 33739025, 2021). "Two key matricellular proteins, well studied for their roles in cancer progression, namely, tenascin C and periostin, were shown to be significantly reduced at both the mRNA and protein levels following hVDAC1 depletion." (PMID 34200480, 2021). "Recent research also revealed that when the POSTN protein is released from activated hepatic stellate cells, it promotes the acquisition of a stem cell phenotype in the surrounding live cancer cells." (PMID 34193219, 2021). "Periostin-promoted lymphangiogenesis is mediated by the increased secretion of VEGF-C in cancer cells and by migration and tube formation via Src and Akt activity." (PMID 34205668, 2021). "Consistent with previous studies on other cancers, our results showed that POSTN also involved in the movement and invasion of RCC 25-27." (PMID 34093819, 2021). "CAFs have been shown to provide stromal support for disseminated cancer cells through a combination of environmental factors, including POSTN and TN-C proteins." (PMID 33808627, 2021). "In the PDX model, most downregulated genes affected by OC-X treatments included MMP9, CXCL12, MMP13, and POSTN within the selected cancer stages." (PMID 34069906, 2021). "An engineered peptide antagonist against periostin also binds to periostin at an integrin-binding site and inhibits periostin function, and thus is expected to see use in peptide therapies to reduce periostin-induced cancer progression and chemoresistance." (PMID 34702952, 2021). "In vitro, serum from TAC-operated mice induced cancer cells proliferation, but depletion of periostin from the serum abrogated this effect." (PMID 34696798, 2021). "Infiltrating cancer cells induce stromal POSTN expression in the secondary target organ—the lungs—to initiate colonization." (PMID 33418894, 2021). "Stromal POSTN has been shown to participate in the regulation of cancer stem cell maintenance and expansion during metastatic colonization." (PMID 34133324, 2021). "Together, these results suggest that modulation by BRCA1+/− iMSCs, which secrete high levels of POSTN, conferred enhanced self-renewal ability on 4T1 cancer cells, which is one of the characteristics of cancer stem cells." (PMID 33513753, 2021). "Among these genes, we focused on periostin, which is already considered a poor prognostic factor in other carcinomas." (PMID 34702952, 2021). "In PDAC, periostin is produced by pancreatic stellate cells and it is shown to establish a microenvironment that is supportive for cancer growth and progression." (PMID 32195182, 2020). "Periostin is a matricellular protein, and excessive periostin deposition plays a pivotal role in cancer cell proliferation, invasion, and dissemination." (PMID 32899501, 2020). "The ability of periostin to promote cell growth in cancer cells has been well studied; either exposure of periostin, transfection of the periostin gene, or co-existence of periostin-producing cells can enhance proliferation of cancer cells." (PMID 32000779, 2020). "Among these stromal biomarkers, periostin stands out in playing a remarkable role during cancer progression." (PMID 32719746, 2020). "The analysis of the OS of NSCLC patients showed a worse prognosis in cases with higher POSTN expression in CAFs compared to patients with low expression of the protein, indicating the influence of this glycoprotein in cancer development." (PMID 32987711, 2020). "Periostin is an extracellular matrix protein, which is known to play an important role in cancer progression." (PMID 32195182, 2020).
cancer (continued). "Majority of samples containing calcifications had strong periostin expression in cancer cells (χ2 test, p = 0.019)." (PMID 31936272, 2020). "When neovascular sprouting is induced, loss of TSP-1 and secretion of new ECM proteins (POSTN, TNC, TGFβ1) trigger reawakening of cancer cells." (PMID 31963820, 2020). "Double immunofluorescence staining for α-SMA and POSTN in NSCLC showed that α-SMA+ fibroblasts were embedded in cancer stroma, which contained abundant immunoreactive POSTN." (PMID 32987711, 2020). "POSTN expression in CAFs increased with clinical cancer stage, grades (G) of malignancy, and lymph node involvement in NSCLC." (PMID 32987711, 2020). "POSTN is an osteoblast specific factor, produced by fibroblasts and secreted to ECM during bone and teeth development, notably produced also by cancer cells and associated with disease progression and drug resistance." (PMID 33287223, 2020). "POSTN has been shown to regulate cancer cell proliferation, angiogenesis, invasion, and metastasis by interacting with integrins such as αVβ1, αVβ3, αVβ5, and α6β4, which activate the Akt/PKB and FAK-mediated signalling pathways." (PMID 32987711, 2020). "Still they are expressed at high levels in H&E(+) lymph nodes possibly indicating that POSTN is a marker for fibroblasts/fibroblast-like cells supporting the cancer cells." (PMID 32049988, 2020). "Additional CAFs-secreted proteins, such as VCAM-1, THBS-2, and POSTN, involved in cancer progression were recently evaluated as potential actionable biomarkers." (PMID 33553157, 2020). "While periostin is involved in numerous biological processes, it sometimes contributes to tumorigenesis by promoting cancer cell survival, invasion, and metastasis actively." (PMID 31988291, 2020). "PSCs on the other hand produce periostin, that stimulates cancer cell growth and increase cancer cell resistance to hypoxia." (PMID 33233631, 2020). "Important ECM proteins include fibronectin, tenascin and periostin that form fibrillar networks and regulate cancer cell adhesion and growth." (PMID 32232008, 2020). "Periostin is a secreted glycoprotein that has also been shown to induce awakening of dormant cancer cells within the lung." (PMID 33014869, 2020). "Recently, more and more research studies have indicated that POSTN is a matrix-specific protein with high expression in the stromal cells surrounding the carcinoma epithelium." (PMID 32987711, 2020). "POSTN recruits Wingless (Wnt) ligands thereby increasing Wnt signaling in cancer cells migrating to the lungs." (PMID 31817646, 2019). "This is further perpetuated by secretion of TGF-β by cancer cells, which stimulates fibroblasts to secrete periostin (POSTN), further activating WNT signaling." (PMID 32010611, 2019). "TW and its transcriptional target POSTN comprise an important signaling axis that promotes mesenchymal phenotypes in cancers including GBM." (PMID 31540485, 2019). "Although overexpression of periostin and its importance in cancer progression was commonly observed in various cancers, periostin seems to interact with different sets of integrins." (PMID 31137693, 2019). "As expected, reduced levels of TIMP3 and elastin (ELN), the major components of elastic fibers, were found in iCCA proteome profiles, while high levels of POSTN were found in all the cancer samples." (PMID 31687002, 2019). "We have determined that the single N-glycosylation site in periostin displays complex N-glycans due to the glycosylation pattern changes in different cancers." (PMID 30911061, 2019). "In other studies, periostin with a molecular mass of 85 and 170 kDa was shown in different cancer cell lines and corneal fibroblasts." (PMID 31412536, 2019). "POSTN interacted with Wnt1 and Wnt3A, which boosted Wnt signaling and facilitated cancer cell growth." (PMID 31817646, 2019). "POSTN, originally isolated as an osteoblast‐specific factor, was illustrated to be involved in the interaction between fibroblasts and cancer cells." (PMID 31304688, 2019).